LINC00466 (long independently transcribed non-coding RNA 466)
Gene: Long non-coding RNA gene on chromosome 1 (63,159,083 to 63,319,666, reverse strand). Ensembl gene ENSG00000224209.
Diseases named in the same sentence as LINC00466 in open-access papers:
LINC00466 is named in the same sentence as 1 disease in open-access papers, as found by Europe PMC text mining. Sharing a sentence is not in itself a finding about the gene and the disease. The quoted sentences say what the papers report.
glioma (1 paper, 2024). A benign or malignant brain and spinal cord tumor that arises from glial cells (astrocytes, oligodendrocytes, ependymal cells). "The study suggests that LINC00466 may exert anti-oncogenic effects in glioma through its interaction with the miR-508/CHEK1 axis, presenting LINC00466 as a potential prognostic and therapeutic target for glioma." (PMID 38893192, 2024).